PEX1 (peroxisomal biogenesis factor 1)
Diseases named in the same sentence as PEX1 in open-access papers:
PEX1 is named in the same sentence as 58 diseases in open-access papers, as found by Europe PMC text mining. Sharing a sentence is not in itself a finding about the gene and the disease. The quoted sentences say what the papers report.
Zellweger syndrome (21 papers, 2009 to 2026). "A notable clinical implication of our study related with high frequency of PEX1 mutations in peroxisome biogenesis disorders, including Zellweger spectrum disorders, in which approximately 65% of cases are linked to PEX1 mutations." (PMID 41267209, 2026). "For example, in Zellweger syndrome, PEX1 mutations lead to peroxisomal dysfunction, resulting in peroxisome loss and severe metabolic defects." (PMID 41267209, 2026). "For example, one case was due to an intronic variant in PEX1(MIM# 602136), in a patient with a known biochemical diagnosis of Zellweger Spectrum Disorder and a heterozygous known pathogenic variant NM_000466.3:c.2916del p.(Gly973fs) in PEX1." (PMID 39763557, 2025). "PEX1-associated Zellweger spectrum disorder (ZSD) results in peroxisomal dysfunction, leading to significant alterations in lipid metabolism." (PMID 40058592, 2025). "Among the novel genes with rare pathogenic variants, PEX1 was linked to Zellweger spectrum disorder, a genetic disorder that causes brain, liver, and kidney problems in newborns." (PMID 40770708, 2025). "The PEX1 gene mutation is associated with peroxisome biogenesis disorder-Zellweger syndrome spectrum (PBD-ZSS) and resulting retinal dystrophies." (PMID 38860019, 2024). "Approximately 80% of PBD patients are classifiedin the Zellweger syndrome spectrum, which is generally caused by mutations in the PEX1, PEX6, PEX10, PEX12, or PEX26 genes." (PMID 33912394, 2021). "Patients with Zellweger syndrome, due to the mutations in PEXs (e.g., PEX1 and PEX5), often develop severe hepatic dysfunction and show elevated inflammation." (PMID 32523050, 2020). "Recently also a knock-in mouse model carrying a missense mutation in the Pex1 gene (Pex1-G844D) was reported, which recapitulates the most frequent mutation in the human Zellweger spectrum disorders with a milder pathology." (PMID 26686055, 2016). "Mutations in PEX1 are the most common primary cause of Zellweger syndrome and account for roughly two thirds of all PBD patients." (PMID 21846392, 2011). "Mutations in PEX1 are the most common primary cause of Zellweger syndrome." (PMID 21846392, 2011). "Since mutations in PEX1 and PEX6 cause the majority of known cases of peroxisome biogenesis disorders such as Zellweger syndrome, insights into Pex1/Pex6 structure and function are important for understanding peroxisomes in human health and disease." (PMID 35805150, 2022). "The protein products of both PEX1 and PEX2 are involved in peroxisome biogenesis and are implicated in a genetic disease associated craniofacial and skeletal abnormalities (Zellweger's syndrome)." (PMID 19557189, 2009). "Only 50 missense mutations (29.4%, PEX1 = 21/85, PEX6 = 27/76, PEX26 = 2/9) were reported to be associated with Zellweger syndrome, which has a severe early-lethal clinical presentation, while the remaining 70.6% of variants are truncating stop or frameshift defects." (PMID 31831025, 2019). "Zellweger spectrum disorders (ZSDs), including archetypal Zellweger syndrome, neonatal adrenoleukodystrophy (NALD) and infantile Refsum disease (IRD), are PBDs caused by mutations in peroxin genes (PEX1, PEX2, PEX3, PEX5, PEX6, PEX10, PEX11β, PEX12, PEX13, PEX14, PEX16, PEX19 or PEX26)." (PMID 40949164, 2025).
peroxisome biogenesis disorder (20 papers, 2011 to 2026). "Muscular hypotonia, global developmental delay, and pigmentary retinopathy in infancy led to a diagnosis of peroxisomal biogenesis disorder due to compound heterozygous PEX1 variants." (PMID 40895213, 2025). "Of the males, four were found to be affected with X-ALD, one was diagnosed with a peroxisomal biogenesis disorder (PEX1 mutations), one was normal on follow-up testing, and data are pending for one." (PMID 35076462, 2022). "In humans, mutations causing dysfunction in PEX1, PEX6, and PEX26—the human equivalents to yeast Pex1, Pex6, and Pex15—are the most prevalent cause of rare genetic disorders called peroxisome biogenesis disorders (PBDs)." (PMID 35805150, 2022). "Heimler syndromes 1 and 2 arise from pathogenic variants in PEX1 and PEX6, respectively, which lead to impaired peroxisome biogenesis." (PMID 33396879, 2020). "In family 3, we identified a pathogenic heterozygous splice-site PEX1 variant, c.1239+1G>T,23 also previously reported in individuals with a severe peroxisome-biogenesis disorder (PBD) and in trans with an ultra-rare missense variant." (PMID 26387595, 2015). "Peroxisome biogenesis disorders within the Zellweger spectrum (PBD-ZSDs) are most frequently associated with the c.2528G>A (p.G843D) mutation in the PEX1 gene (PEX1-G843D), which results in impaired import of peroxisomal matrix proteins and, consequently, defective peroxisomal functions." (PMID 33869228, 2021). "The AAA-ATPase Pex1/Pex6 drives protein import into peroxisomes and is thus a key step in peroxisome formation and a common culprit for peroxisome biogenesis disorders." (PMID 35805150, 2022). "Heimler syndromes 1 and 2 are at the mildest end of the PBD spectrum, and are caused by pathogenic variants in PEX1 and PEX6, respectively." (PMID 33396879, 2020). "Of relevance, mutations in two REM components, PEX1 and PEX6, have been shown to be the most frequent cause of peroxisomal biogenesis disorders accounting for 76% of all cases." (PMID 31652724, 2019). "Pex1 and Pex6 form a heterohexameric motor essential for peroxisome biogenesis and function, and mutations in these AAA-ATPases cause most peroxisome-biogenesis disorders in humans." (PMID 29321502, 2018). "To test if the induction of peroxisomal β-oxidation by BF caused the reduction in C26:0 levels, we incubated fibroblasts from patients with a peroxisomal biogenesis disorder (PEX1, PEX6 and PEX26) with BF and measured the effect on D3-C26:0 de novo synthesis." (PMID 22447153, 2012). "Altogether, our findings suggest a novel regulatory mechanism for PEX1/PEX6 hexamer assembly and highlight the potential of protein stabilization as a therapeutic strategy for peroxisome biogenesis disorders arising from the G843D mutation and other PEX1 hypomorphs." (PMID 40158855, 2025). "Pex1 and Pex6 were originally identified as genes necessary for yeast to grow on oleate, which requires peroxisomes, and were subsequently recognized as dysfunctional in humans with certain peroxisome biogenesis disorders." (PMID 35805150, 2022). "Hence, it appears that some of the retinal pathologies observed in peroxisome biogenesis disorders are recapitulated in the Pex1 knock-in mice, including photoreceptor dysfunction, but, in contrast to the patients, anomalies of the RPE were not reported in the mice." (PMID 33921065, 2021).
Retinal dystrophy (5 papers, 2019 to 2026). Retinal dystrophy is an abnormality of the retina associated with a hereditary process. "It is caused by hypomorphic mutations in peroxisomal assembly genes, most commonly PEX1 and PEX6, and is characterized by sensorineural hearing loss, amelogenesis imperfecta, and retinal dystrophy." (PMID 42074478, 2026). "Ten families had variants in genes related to a syndromic disease with retinal dystrophy (COL9A1, CEP290, PCDH15, LRP5, PEX1, CFH, COL2A1 and COL11A1)." (PMID 35457050, 2022). "Furthermore, at least one mutation in one patient affects the AAA-ATPase region (PEX1 and PEX6) or PEX6 binding site (PEX26) when HS patients have retinal dystrophy." (PMID 31831025, 2019).
microcephaly (3 papers, 2022 to 2023). A congenital or acquired developmental disorder in which the circumference of the head is smaller than normal for the person's age and sex. "A rare homozygous variant in PEX1 gene (p.G843D) was identified in a child boy (DSD 17) with syndromic form of DSD, including microcephaly, partial agenesis of the corpus callosum, dysmorphic features and unilateral cryptorchidism." (PMID 36631813, 2023).
Refsum disease (3 papers, 2018 to 2025). Refsum disease, biochemically characterised by phytanic acid accumulation, belongs to the group of leucodystrophic diseases. "Severe alleles in PEX genes lead to severe clinical presentations, but in recent years, the mild presentations due to PEX mutations have expanded from phenotypes labeled as “infantile Refsum disease” to include atypical ataxia in PEX16 and Heimler syndrome in PEX1 and PEX6." (PMID 39605732, 2024).
Hearing Loss (2 papers, 2022). "Such phenotype, if also present in PEX1 patients, would predict high sensitivity to noise induced hearing loss along with progressive hearing loss." (PMID 36552747, 2022). "As sensory hair cells are particularly vulnerable to metabolic changes, we hypothesize that mutations in PEX1 lead to oxidative stress affecting hair cells of the inner ear, subsequently resulting in hair cell degeneration and hearing loss." (PMID 36552747, 2022).
retinal degeneration (2 papers, 2025). Degeneration of the retina. "Accumulation of phytanic acid has been linked to retinal degeneration, brain and nerve damage; it could therefore be one of the causes for the retinal phenotype in the adult pex1–/– fish and decreased locomotor behavior in the larvae." (PMID 41268363, 2025). "Our MSI results in the PEX1-G844D RPE underscore the broad impact of Pex1 deficiency on lipid metabolism and its potential role in driving inflammation and retinal degeneration." (PMID 40058592, 2025). "Globally, elevated VLCFAs in the PEX1-G844D model can disrupt membrane integrity and induce oxidative stress, exacerbating retinal degeneration." (PMID 40058592, 2025). "Considering that ZSD patients develop retinal degeneration and glaucoma, we sought to assess whether similar hallmarks are present in our pex1–/– zebrafish model." (PMID 41268363, 2025). "Moreover, studies in the Pex1-G844D mouse confirmed a correlation between the accumulation of VLCFAs and retinal degeneration, altogether showing the important role of functional peroxisomes to support vision health." (PMID 41268363, 2025). "Thus, we generated a knock-in (PEX1-G844D) mouse model representing the common human PEX1-c.2528G>A allele (encoding PEX1-G843D) to study pathophysiology and develop therapies, and found that it has classic features of milder ZSD, including retinal degeneration." (PMID 40058592, 2025).
X-linked adrenoleukodystrophy (2 papers, 2021). X-linked adrenoleukodystrophy (X-ALD) is a peroxisomal disorder resulting in cerebral demyelination, axonal dysfunction in the spinal cord leading to spastic paraplegia, adrenal insufficiency and in some cases testicular insufficiency.
autosomal recessive retinitis pigmentosa (1 paper, 2022). Autosomal recessive retinitis pigmentosa (RP) is an autosomally recessive inherited retinal dystrophy leading to progressive loss of the photoreceptors and retinal pigment epithelium and resulting in blindness usually after several decades. "Mutations in the remaining four genes, namely, SLCO1B1, CNGA1, PRSS12, and PEX1, have associations with autosomal diseases, such as autosomal recessive retinitis pigmentosa and non-syndromic intellectual disability." (PMID 35912179, 2022).
cardiac arrhythmia (1 paper, 2020). Any disturbances of the normal rhythmic beating of the heart or MYOCARDIAL CONTRACTION. "On the other hand, KD of the key factors (peroxines) involved in peroxisomal import process (Pex5, Pex1, and Pex14) in oenocytes significantly induced cardiac arrhythmia." (PMID 32523050, 2020).
Cirrhosis (1 paper, 2026). A chronic disorder of the liver in which liver tissue becomes scarred and is partially replaced by regenerative nodules and fibrotic tissue resulting in loss of liver function. "The PEX1-p.G843D (c.2528G>A) allele, present in approximately 30% of individuals with ZSD, frequently results in chronic liver disease that can progress to cirrhosis, hepatocellular carcinoma and degraded neurological health." (PMID 41981313, 2026).
colorectal carcinoma (1 paper, 2025). A malignant epithelial neoplasm that arises from the colon or rectum and invades through the muscularis mucosa into the submucosa. "To create PEX1G843D model cell lines, we first used Cas9 gene editing to create clonal homozygous N-terminal FLAG-PEX1 and heterozygous C-terminal PEX1-FLAG cell lines in human male colorectal carcinoma HCT116 cells." (PMID 40158855, 2025).
cystic fibrosis (1 paper, 2025). Autosomal recessive disorder caused by pathogenic variants in the CFTR gene (cystic fibrosis transmembrane conductance regulator), which encodes a chloride and bicarbonate channel expressed in epithelial cells, and follow the diagnosis criteria. "Instead, strategies to stabilize the residual protein levels of PEX1 hypomorphs could be modeled on promising approaches to treating other diseases exacerbated by overzealous protein quality control such as cystic fibrosis." (PMID 40158855, 2025).
Hepatic steatosis (1 paper, 2025). Steatosis is a term used to denote lipid accumulation within hepatocytes. "A prominent phenotype in pex1–/– larvae was hepatic steatosis, accompanied by increased TG levels." (PMID 41268363, 2025). "However, 96% of pex1–/– larvae at 11 dpf showed darkening of the liver, and hepatic steatosis was confirmed using oil red (ORO) staining at 13 dpf." (PMID 41268363, 2025).
hyperopia (1 paper, 2019). A refractive error in which rays of light entering the eye parallel to the optic axis are brought to a focus behind the retina, as a result of the eyeball being too short from front to back. "As well as the previously reported phenotypic features of RP with CME, these patients also showed short axial lengths and hyperopia suggesting that PEX1 mutation-associated ocular involvement can be developmental (short axial length) and degenerative (RP)." (PMID 31831025, 2019).
Hyperoxaluria (1 paper, 2024). Increased excretion of oxalates in the urine. "It has been associated with hyperoxaluria with NL and NC with variants in PEX1 and PEX3, likely with variants in PEX5, and possibly with variants in PEX6, PEX7, PEX10, PEX11, PEX12, PEX13, PEX16, and PEX26." (PMID 38606357, 2024). "It has been associated with hyperoxaluria with NL and NC with variants in PEX1, likely with variants in PEX5, and possibly with variants in PEX3, PEX6, PEX 10, PEX 12, PEX13, PEX14, PEX16, PEX19, and PEX26." (PMID 38606357, 2024).
infertile (1 paper, 2025). "In addition, we suspect that pex1–/– animals are infertile, as repeated crossing attempts failed to produce any viable offspring." (PMID 41268363, 2025).
Niemann-Pick disease type C (1 paper, 2020). NPC is a complex lipid storage disease mainly characterized by the accumulation of unesterified cholesterol in the late endosomal/lysosomal compartment.
osteosarcoma (1 paper, 2025). A usually aggressive malignant bone-forming mesenchymal neoplasm, predominantly affecting adolescents and young adults. "In osteosarcoma, decreased NSUN6 expression reduced m5C modifications on PEX1 and PEX3 mRNA, leading to PEX1 and PEX3 instability by losing the binding of the m5C recognition protein YBX1." (PMID 41462962, 2025).
parasitic diseases (1 paper, 2024). "As PEX1 turned out to be essential for trypanosomatid parasites, it could provide a suitable drug target for parasitic diseases." (PMID 38510966, 2024).
scrapie (1 paper, 2022). A fatal disease of the nervous system in sheep and goats, characterized by pruritus, debility, and locomotor incoordination. "Peroxisomal biogenesis factor 1 (PEX1) is a gene encoding the peroxin 1 protein that is involved in the peroxisome biogenesis specifically in importing peroxisomal matrix proteins and was upregulated in scrapie animals." (PMID 35252421, 2022). "In our study, we detected an upregulation of PEX1 gene in naturally infected scrapie animals that were significantly correlated with spongiosis and PrPSc accumulation, suggesting that peroxisome activity might as well be compromised in scrapie." (PMID 35252421, 2022). "Of all the selected genes, significant changes between the control and scrapie animals were found in the expression of five genes: PCDH19, SNCG, WDR45B, PEX1, and CABIN1." (PMID 35252421, 2022). "We identified many DMRs between the control and scrapie animals, some of them belonging to genes with possible neuroprotective roles against neurodegeneration (SNCG and WDR45B) and to genes that may facilitate or contribute to scrapie disease progression (PCDH19, PEX1, and CABIN1)." (PMID 35252421, 2022).
cancer (3 papers, 2025). A tumor composed of atypical neoplastic, often pleomorphic cells that invade other tissues. "It was observed that cancers carrying the NRAS mutation differ in their Peroxisomal Biogenesis Factor 1 (PEX1) expression that was reported to be crucial for generation of lipids with polyunsaturated acids making them sensitive to oxidation." (PMID 40382332, 2025).
metabolic disorders (1 paper, 2025). "Additionally, biallelic variants were detected in the CTSA and PEX1 genes, associated with severe metabolic disorders that often present with non-immune foetal hydrops." (PMID 41153384, 2025).
retinopathy (1 paper, 2025). "To understand whether the lipid changes observed in the RPE of PEX1-G844D mice could be directly linked to retinopathy progression, we investigated whether the lipids we identified by MSI in our model had already been described in different mouse models of RD." (PMID 40058592, 2025). "Overall, while the observed lipid changes are associated with PEX1-G844D-induced retinopathy, it is unknown whether they are related to the onset or progression of this disorder, or whether they are consequent to disease pathology." (PMID 40058592, 2025). "To understand whether the lipid changes observed in the RPE of PEX1-G844D mice could be driving retinopathy progression, we compared our results with those of different RD mouse models." (PMID 40058592, 2025). "Regardless, the lipid changes identified when tissues are damaged could present a lipid signature of PEX1-G844D-induced retinopathy and be candidate biomarkers if detectable in blood or vitreous humor." (PMID 40058592, 2025).
PEX1 also shares sentences with these, for which no sentence is quoted: Zellweger spectrum disorders (12 papers); genetic disorder (3); infection (3); amelogenesis imperfecta (2); Ataxia (2); Primary microcephaly (2); Adrenal insufficiency (1); B-cell non-Hodgkin lymphoma (1); Breast Invasive Carcinoma (1); ciliopathies (1); cognitive delays (1); connective tissue disorder (1); dysplasia (1); enamel hypoplasia (1); epilepsy (1); Fraser syndrome (1); glaucoma (1); heart malformations (1); hepatocellular carcinoma (1); Intellectual disability (1); kidney disease (1); leukodystrophy (1); macular degeneration (1); medulloblastoma (1); Nail dystrophy (1); neurodevelopmental disorder (1); osteogenesis imperfecta (1); Pigmentary retinopathy (1); rhizomelic chondrodysplasia punctata type 1 (1); sensorineural hearing loss (1).
A further 4 diseases each share a sentence with PEX1 in 1 paper.